INS (insulin)
Diseases named in the same sentence as INS in open-access papers (continued):
Sharing a sentence is not in itself a finding about the gene and the disease.
cancer (continued). "However, if the use of insulin analogues and conventional insulin secretagogues, which lead to increased levels of circulating insulin, has been associated with increased risk of cancer, metformin and thiazolidinediones (TZDs) may have the potential to prevent tumor development." (PMID 34681797, 2021). "And the use of metformin can lower blood sugar and insulin levels, thereby inhibiting cancer cell proliferation and tumor growth." (PMID 33976288, 2021). "GLUT4 is an insulin-stimulated glucose transporter, and glucose uptake is dependent on insulin stimulation in cancer cell lines." (PMID 34552932, 2021). "Although these associations do not prove causation there are experimental data to support a role of the IGFs and insulin in the development of cancer." (PMID 34290976, 2021). "High insulin levels (hyperinsulinemia) affect cancer development by directly stimulating the insulin receptor (IR) and/or indirectly through increasing the level of circulating Insulin Like Growth Factor 1 (IGF-1)." (PMID 33673109, 2021). "Population studies provide substantial direct and circumstantial evidence that cancer risk and cancer prognosis are influenced by IGF-1 and insulin levels." (PMID 34804946, 2021). "Insulin can promote cancer through its mitogenic actions and the INSR is often overexpressed in tumour cells." (PMID 34572888, 2021). "In fact, IR-A is predominantly expressed in poorly differentiated cells (e.g., fetal and cancer cells), while IR-B is predominant in mature insulin target tissues such as liver, muscle and adipose tissue." (PMID 34445431, 2021). "Insulin/IGF-1R signal is also involved in the crosstalk between cancer cells and matrix, and research on compounds targeting Insulin/IGF signal in the treatment of PDAC entered into clinical trials in phase II." (PMID 34067040, 2021). "As a risk factor for the occurrence and development of a variety of cancers, insulin participates in metabolic, cell survival and proliferation signaling pathways." (PMID 34485124, 2021). "Insulin resistance does not occur in epithelial cells, of which many types of cancer are derived, resulting in relatively high insulin and glucose exposure of cancer cells in T2DM patients 12,13." (PMID 33391452, 2021). "In this context, insulin signaling plays a fundamental role, in modulating both heart metabolism and cancer growth, with AMPK being one of the main regulators." (PMID 33547494, 2021). "As the MAPK pathway triggers the transduction responses mediated by both estrogen and insulin signaling in cancer cells, we noted that either ICI or OSI‐906 prevents the ERK1/2 phosphorylation by both E2 and insulin in BCAHC‐1 cells." (PMID 34841688, 2021). "AZGP1, an important protein involved in insulin sensitivity and plays a role in metabolism and cell cycle, which are known to be altered in cancer progression." (PMID 33564003, 2021). "ACLY (the main enzyme in the conversion of citrate derived from glycolytic metabolism into acetyl-CoA) is overexpressed in many cancer cell lines that are stimulated by insulin, growth factors, and hyperglycemia." (PMID 36046117, 2021). "As glutamine is involved in cancer cell proliferation, we also tested the effect of insulin on GS induction." (PMID 34575972, 2021). "The PI3K p110α inhibitor BYL719 (alpelisib) is currently an approved cancer therapeutic; however, genetic studies in rodents suggest that long-term suppression of insulin/IGF1 signaling mediated PI3K p110α can extend life and healthspan of aged mice." (PMID 33503847, 2021). "In the following paragraph, we will describe how advanced cancer itself dramatically interferes with the cardiac insulin pathway further exacerbating drug-induced toxicity." (PMID 33547494, 2021).
cancer (continued). "PTPRN2, involved in processes ranging from insulin secretion to metastasis and cell migration, is widely reported to be aberrantly methylated in cancer and non-cancer conditions." (PMID 33461589, 2021). "Little is known about the role of CEACAM8 in cancer, making it hard to assess the consequences of an insulin-induced CEACAM8 upregulation." (PMID 33690729, 2021). "Through transferring of let-7a miRNA, hypoxic cancer exosomes suppress the insulin-Akt-mTOR signaling pathway and evade host immunity to enhance cancer progression." (PMID 34263260, 2021). "Since cancer cells depend heavily on glycolysis, by reducing glucose, insulin, IGF-1 levels, plus lactate production, KDs potentially induce selective starvation in cancer cells." (PMID 34579079, 2021). "At the time of cancer diagnosis, 25% of patients with DM were using insulin; 1 year after cancer diagnosis, this increased to 35%." (PMID 34046189, 2021). "Increased insulin and IGF1 levels have been shown to correlate with an increased risk of several cancer types." (PMID 34191793, 2021). "It forms a protein involved in insulin signaling, cancer, and cytokines (involved in the immune system), and also in adipocyte maturation." (PMID 34366888, 2021). "Although PHD3 has been reported to influence cancer cell metabolism and liver insulin sensitivity, relatively little is known about the effects of this highly conserved enzyme in insulin-secreting β cells in vivo." (PMID 34264866, 2021). "The plausible mechanisms that explain this association focus largely on inhibiting growth stimuli and metabolic processes within cancer cells and can be divided into insulin-dependent and -independent mechanisms that alter cancer cell growth." (PMID 34680546, 2021). "During cancer development, insulin, IGFs, and ovarian steroid hormones (estrogen and progesterone) can act synergistically." (PMID 34535145, 2021). "In the present study, the expression of miR-221 in insulin-treated MCF-7cells in response to the anti-cancer drug doxorubicin, was investigated." (PMID 34308576, 2021). "Enpp2 is an ectoenzyme expressed and secreted by many cell types, and plays roles in blood vessel formation, cancer cell migration, insulin resistance in muscle cells, and homing and inflammatory responses by lymphocytes." (PMID 34829956, 2021). "For instance, tumor growth negatively affects plasma insulin and glucose levels in cancer-bearing mice." (PMID 33419963, 2021). "The proteins downregulated when the endometrial cells were exposed to high concentrations of insulin were associated with protein digestion and absorption, ECM–receptor interaction, and proteoglycans in cancer." (PMID 33693651, 2021). "From that figure, we received the signaling pathways involved in endocytosis, MAPK signaling, protein processing in the endoplasmic reticulum, cancer development, oxidative phosphorylation, insulin as those that were primarily affected." (PMID 34830111, 2021). "The main enriched KEGG pathways were protein digestion and absorption (14 genes), microRNAs in cancer (24 genes), insulin signaling pathway (24 genes)." (PMID 34889903, 2021). "Obviously, RCTs last too short to exert all beneficial metabolic (decreased body weight, improved insulin sensitivity) and anti-inflammatory effects of SGLT-2 inhibitors in terms of cancer risk." (PMID 33562380, 2021). "Expression of the respective receptors is detected on cancer cells of different origins and several cancers are driven by insulin and IGF-1 in vitro." (PMID 33987528, 2021). "The biological pathways linking adiposity with cancer development are incompletely understood, but likely involve alterations in insulin signaling, sex hormone pathways and adipose tissue‐derived inflammation." (PMID 33038280, 2021). "Peng et al39 demonstrated that miR‐486 is capable of regulating insulin growth factors, reducing cancer cell growth and migration, and inducing apoptosis in NSCLC." (PMID 32965722, 2021).
cancer (continued). "There were 16 patients (18.6%) who changed their DM therapy within 1 year after the squamous carcinoma cancer diagnosis; seven patients (43.8%) used insulin within 1 year after the cancer diagnosis." (PMID 34046188, 2021). "Among the adverse prognostic factors recognized in cancers as breast, colon and prostate cancer, high insulin levels have been widely described." (PMID 35008275, 2021). "The JAK/STAT signaling pathway, Insulin signaling pathway and Pathways in cancer had the best correlation with a correlation coefficient of approximately 0.36." (PMID 33245478, 2021). "And the KEGG pathway analysis indicated that DE mRNAs mainly involved in pathways including bacterial invasion of epithelial cells, proteoglycans in cancer, insulin signaling pathway and so on with P<0.05." (PMID 33961683, 2021). "PCRD is most likely a paraneoplastic phenomenon resulting from factors released by the cancer that negatively impact islet cell function as well as peripheral insulin sensitivity." (PMID 34680372, 2021). "Based on the results, altered metabolism (aerobic glycolysis, insulin resistance, myokines), oxidative stress, gene expression and apoptosis were hot-research mechanisms of exercise on cancer." (PMID 35096970, 2021). "The serum levels of cytokines, insulin, ghrelin, leptin, adiponectin, cortisol, and thyroid hormones were altered during cancer progression and the CCRT course." (PMID 34578846, 2021). "Abnormal expression of insulin gene enhancer-binding protein 1 (ISL1) has been demonstrated to be closely associated with cancer development and progression in several cancers." (PMID 34753990, 2021). "Patients on insulin or insulin-secreting agents (sulphonylureas) are at higher risks of cancer than patients on oral insulin-sensitizing agents (metformin or thiazolidinediones)." (PMID 33671547, 2021). "Presumably, decreasing the presentation of glucose by dietary carbohydrate restriction at the cellular and the epigenetic programming resulting from elevated insulin concentrations would be expected to reduce tumorigenesis and progression of cancer." (PMID 34684564, 2021). "The results showed that treatment of the MCF-7 cells with insulin reduced the anti-cancer effects ofdoxorubicin." (PMID 34308576, 2021). "IGF2mediates mitogenic signaling and survival in cancer, while insulin stimulates glucose uptakeand metabolic activity." (PMID 33988719, 2021). "While the current evidence is mostly focused on insulin and glucose pathways, the effects of fasting on lipid profiles are underexplored in cancer settings, which warrants further investigations." (PMID 34684421, 2021). "Further research will be needed to clarify the role of low skeletal muscle mass‐induced alterations in insulin resistance and insulin‐like growth factors in the progression of cancer." (PMID 32478975, 2021). "This evidence prompted the potential use of metformin as a safe drug to lower circulating insulin levels not only in diabetic patients, and in turn to counteract cancer progression." (PMID 35008275, 2021). "Another factor is the interplay with cancer and anticancer treatment, as both can influence skeletal muscle mass, systemic inflammation, insulin‐dependent glucose handling, protein status and pharmacokinetics of anticancer drugs." (PMID 32478975, 2021). "Conversely, physical inactivity, which is often a consequence of cancer, leads to decreased insulin action." (PMID 33801684, 2021). "Aberrant signaling through insulin (Ins) and insulin-like growth factor I (IGF1) receptors contribute to the risk and advancement of many cancer types by activating cell survival cascades." (PMID 34191793, 2021). "We also identified some novel mutations in genes that are closely related to DNA repair-, cancer- or metabolism-related signaling pathways, including PI3K/Akt, mTOR, AMPK, FoxO, and insulin signaling." (PMID 34805171, 2021).
cancer (continued). "At present, several human clinical trials are investigating insulin-lowering treatments as adjuvants to cancer treatments." (PMID 33987528, 2021). "High levels of insulin, C-peptide, and IGF-1 have been associated with an increased risk of certain cancers in epidemiological studies, including breast cancer, colorectal cancer, and prostate cancer." (PMID 33467499, 2021). "The differential expressions of miRNAs between the CRSwNP and control groups were enriched in “pathways in cancer,” “endocytosis,” “thyroid hormone signaling pathway,” “salivary secretion,” “regulation of actin cytoskeleton,” “insulin secretion,” and so on." (PMID 34124144, 2021). "In the following years, many studies analyzing the relationship between exogenous insulin and cancer were published." (PMID 33562380, 2021). "Reductions in abdominal and visceral adiposity improve insulin sensitivity, lipid profile and cytokines, which consequently reduce the risk of CVD and some cancer types." (PMID 33261185, 2020). "Presumably, the responsible agent is cancer-secreted lactate that is able to reduce extracellular pH and binding affinity between insulin and its receptor, thus provoking the host IR." (PMID 32426290, 2020). "These proinflammatory cytokines not only impair the action of insulin in metabolic tissues, but also favor cancer development." (PMID 32764462, 2020). "In insulin resistance, insulin and insulin-like growth factors can also significantly improve cancer development with proliferation promotion and antiapoptotic impacts." (PMID 33552985, 2020). "Pharmacological modulation of aging can be observed by the small-molecular inhibitors against TOR and S6K1 in alleviating age-related disorders like aberrant insulin signaling and cancer." (PMID 32526825, 2020). "Since many cancer cells overexpress both the insulin and IGF-I receptors and due to the high sequence homology between these receptors, hybrid receptors consisting of one insulin αβ hemi-receptor and one IGF-IR αβ hemi-receptor can also form." (PMID 32365498, 2020). "As such, the connection between RSKS-1/S6K and AMPK, the insulin pathway, and cancer-related mircoRNAs is also worth investigating." (PMID 33375360, 2020). "The role of Rosi in preventing tissue atrophy is consistent with published reports demonstrating TZDs effects on alleviating adipose and muscle wasting in cancer cachexia and in promoting insulin sensitivity in muscle of aged rats." (PMID 33219735, 2020). "Previous studies have reported that the ratio of IR/IGF-1R expression is important in determining the sensitivity of the cancer cells to the effects of insulin." (PMID 32393319, 2020). "Then KEGG analysis showed that mRNAs included in this network played important roles in insulin signaling pathway, glycine, serine and threonine metabolism, pathways in cancer, lysosome, and apoptosis." (PMID 33176720, 2020). "Targets of dysregulated let-7 are known to contribute to glucose homeostasis and insulin signaling as well as cancer pathophysiology." (PMID 32466456, 2020). "Possible mechanisms, functionally linking hypoxia in insulin-resistant conditions to cancers, are further discussed in the chapter below." (PMID 33266015, 2020). "Nevertheless, we suggest that reduced WISP-1 partly contributes to improvements in insulin sensitivity and cancer prognosis." (PMID 32616883, 2020). "We found that the migration and invasion of both types of cancer cells were increased by insulin treatment." (PMID 32631390, 2020). "Target prediction analysis showed that miR-186-5p potentially targets Gsk3b, which is involved in many pathways such as the PI3K-akt signaling pathway, ErbB signaling pathway, pathways in cancer, and insulin signaling pathway." (PMID 33133155, 2020).
cancer (continued). "First, reduced blood insulin concentrations at the cancer cell membrane results in less binding to the insulin receptor with resulting downstream inhibition of the PI3K-Akt-mTOR (PAM) signaling cascade, as well as the RAS-RAF-MEK-ERK pathway." (PMID 33270630, 2020). "CEACAM1 has important roles in angiogenesis, regulation of insulin action and immune responses and is crucial in the progression and metastasis of a range of cancers, exerting oncogenic as well as tumor suppressive actions." (PMID 33075095, 2020). "The intersection of insulin signaling, diabetes, and cancer represent an active area of oncometabolic research, although the mechanistic underpinnings of these relationships remain incompletely understood." (PMID 33233470, 2020). "There is emerging evidence that insulin signaling plays a role in macrophage switching during cancer initiation and progression." (PMID 32153503, 2020). "This dual-pathway activation is important for insulin's ability to promote cellular motility and cancer cell invasion." (PMID 32153503, 2020). "Unrestricted tumor growth requires a permanent supply of glucose that can be obtained from cancer-stimulated hepatic glucose production and/or glucose redirecting from host insulin resistant tissues to cancer cells." (PMID 32426290, 2020). "Many of these pro-cancer, insulin-initiated signal transduction cascades rely on the insulin receptor (INSR) tyrosine kinase family." (PMID 33233470, 2020). "In our study, we found that the downstream target genes of miR-17 were enriched in MAPK pathways, the tyrosine kinase signaling pathway, cell cycle pathways, and insulin signaling pathway, all of which are involved in cancer formation." (PMID 32118734, 2020). "The other (blue) can redirect the glucose supply from the host insulin-resistant tissues to cancer cells." (PMID 32426290, 2020). "AKT2 is one of the key molecules that involves in the insulin-induced signaling and the development of cancer." (PMID 32252758, 2020). "Meanwhile, in the past decade, interest has grown in insulin inhibition as a potential cancer therapeutic adjunct." (PMID 33270630, 2020). "Accumulating evidence suggests that citrate is involved in numerous physiological and pathophysiological processes such as inflammation, insulin secretion, neurological disorders, and cancer." (PMID 33282912, 2020). "In the MC-0 vs. MC-50 group, the target gene enrichment pathways included transcriptional misregulation in cancer, the insulin signaling pathway, protein processing in the endoplasmic reticulum, microbial metabolism in diverse environments, and endocytosis." (PMID 31936480, 2020). "An ideal implementation would be to consider using drug pumps like those used in insulin management for continuous measurement and administration of cancer therapeutics." (PMID 33290430, 2020). "AKT2 has been well studied in cancer and insulin-mediated signaling, and in our study we demonstrate the function of AKT2 in B lymphocytes." (PMID 32252758, 2020). "The genes dysregulated during long-term stress (on day 14) are involved in the pathways of various homeostatic processes, including cell cycle and cancer regulation and insulin signaling." (PMID 32103041, 2020). "Glucose uptake and increased insulin signaling have been shown by DFO treatment in cancer and rat liver cells." (PMID 31960628, 2020). "Long-acting insulin analogs have been demonstrated to stimulate cancer cell proliferation in vitro more than native insulin." (PMID 32156062, 2020). "The increased risk of RCC development in obese patients has been also ascribed to deregulation of insulin (IN) and insulin-like growth factors (IGFs) signalling since these pathways are believed to be engaged in tumorigenesis and cancer progression." (PMID 33008076, 2020). "Pharmacological inhibition of S6K1 kinase alleviates age-related disorders like aberrant insulin signaling and cancer." (PMID 32526825, 2020).